IDH2 (isocitrate dehydrogenase (NADP(+)) 2)
Diseases named in the same sentence as IDH2 in open-access papers (continued):
Sharing a sentence is not in itself a finding about the gene and the disease.
myelodysplastic/myeloproliferative neoplasm (1 paper, 2025). A category of clonal hematopoietic disorders that have both myelodysplastic and myeloproliferative features at the time of initial presentation. "Furthermore, somatic mutations in IDH2 have been observed in the histiocytes of granulomatous lesion in patients with myelodysplastic/myeloproliferative neoplasms." (PMID 39839460, 2025).
neuroendocrine carcinoma (1 paper, 2022). A malignant neuroendocrine neoplasm composed of cells containing secretory granules that stain positive for NSE and chromogranin. "Furthermore, it has been suggested that IDH2 mutated neuroendocrine carcinomas and IDH2 mutated SNUCs may represent the same entity, due to their epigenetic similarity." (PMID 36443295, 2022).
neuroendocrine tumors (1 paper, 2023). "The latest advances in the known genetics of neuroendocrine tumors such as SUCLG2 (succinyl-CoA ligase ß Subunit G2, an oxygen-sensing domain in hypoxia inducible factor 2) and IDH2 (isocitrate dehydrogenase 2) were recently reported." (PMID 36936415, 2023).
oncocytoma (1 paper, 2018). "Thus, we studied the expression of IDH2 by immunohistology in different renal tumors, to analyze whether this miR has a similar function in oncocytomas." (PMID 30116406, 2018).
renal cell carcinoma (1 paper, 2021). "Dysregulation of Sirt5/IDH2 partially contributes to Sun resistance by disturbing mitochondrial functions and affecting antioxidant capacity of renal cell carcinoma cells." (PMID 33455080, 2021).
retinal degeneration (1 paper, 2018). Degeneration of the retina. "Furthermore, we used RT-PCR to confirm the expression of Idh2 in the mouse retina, as well as all three subunits of Idh3, indicating that it is not lack of IDH2 in the retina that results in retinal degeneration." (PMID 30478029, 2018).
skin nodules (1 paper, 2024). "The patient with skin nodules and the pathology diagnosed BPDCN, the next generation sequencing of skin nodules showed mutations of IDH2 and ASXL1." (PMID 38527844, 2024).
spinal cord astrocytoma (1 paper, 2021). A low or high grade astrocytoma that arises in the spinal cord. "A small group of spinal cord astrocytomas harbors isocitrate dehydrogenase (IDH) mutations, namely, IDH1 or IDH2 mutations." (PMID 34685506, 2021).
Stroke (1 paper, 2019). Sudden impairment of blood flow to a part of the brain due to occlusion or rupture of an artery to the brain. "Error quickly decreased by the end of the first stroke-dynamics/healthy target practice block (RM ANOVA for IDH trials: F = 7.7, P < 0.001; pairwise comparison for IDH1 Early vs. IDH2: P < 0.05) but did not exhibit further decreases after that." (PMID 30403561, 2019).
undifferentiated carcinoma (1 paper, 2025). A usually aggressive malignant epithelial neoplasm composed of atypical cells which do not display evidence of glandular, squamous, or transitional cell differentiation. "The second group, sinonasal tumors with IDH2 mutations (n = 7), displayed a distinct CIMP phenotype, histological features consistent with high-grade undifferentiated carcinoma, diffuse cytokeratin expression, and universal IDH2 R172 hotspot mutations." (PMID 40710426, 2025).
undifferentiated pleomorphic sarcoma (1 paper, 2023). An undifferentiated soft tissue sarcoma characterized by the presence of a pleomorphic malignant cellular infiltrate. "The presence of IDH1/IDH2 mutations helps distinguish CS from chondroblastic osteosarcoma and DDCS from undifferentiated pleomorphic sarcoma (UPS) of bone." (PMID 36926116, 2023).
vulva tumors (1 paper, 2015). "We report a detailed study of 25 vulva tumors [22 SCC, 2 MM, 1 atypical squamous cell hyperplasia (AH)] analyzed for expression of the high-mobility group AT-hook family member genes HMGA2 and HMGA1, for mutations in the IDH1, IDH2 and TERT genes, and for methylation of the MGMT promoter." (PMID 25823555, 2015).
tumor (364 papers, 2010 to 2026). "Three cases showed TET2 or IDH2 mutation in sorted cells that were undetected in the whole‐tissue section, likely due to low tumor content and sub‐clonal mutation." (PMID 40510016, 2025). "Nevertheless, the significance of mutations in IDH1 and IDH2 proteoforms can differ based on the type of tumor and associated genetic changes." (PMID 41516249, 2025). "Using multiple public and in‐house CRC datasets, we then identified IDH mutations at the hotspots (IDH1 codons 132 and IDH2 codons 140 and 172) frequently mutated in other tumour types." (PMID 40545636, 2025). "The oncometabolite R-2HG is produced by IDH1 or IDH2 mutations in tumor cells and accumulated in the tumor microenvironment to levels up to 30 mM." (PMID 41367876, 2025). "Molecular diagnosis via NGS confirmed IDH1 R132H (in 11 tumors), IDH1 R132G (1 tumor), IDH1 R132L (1 tumor), and IDH2 R172G (1 tumor) mutations." (PMID 41373636, 2025). "Mutations in the metabolic enzymes IDH1 and IDH2 which are enriched in tumours with a high expression of mitochondrial genes, are potentially therapeutic targets." (PMID 38877653, 2024). "RPLS scores were lower in tumours harbouring IDH1 or IDH2 mutations (all 3 cohorts with data available), as well as FGFR2 fusions (2/3 cohorts)." (PMID 37758326, 2024). "IDH mutations, particularly in IDH1 and IDH2 genes, are mutually exclusive and have significant implications for tumor behavior and patient prognosis." (PMID 38167551, 2024). "This trend was also confirmed in MACS tumor-associated macrophages (TAMs) isolated from transplanted tumor tissue of IDH2-deficient mice." (PMID 39256649, 2024). "Research into the carcinogenesis of SNUC points to a correlation between tumor development and recurrent IDH2 R172 mutations." (PMID 39565059, 2024). "The average tumor size in the IDH2-deficient mouse group was significantly smaller than in the WT mouse group." (PMID 39256649, 2024). "IDH2 deficiency in macrophages was associated with inhibited tumor growth and epithelial–mesenchymal transition." (PMID 39256649, 2024). "Next, we performed a co-culture using a transwell system to determine the mechanism through which IDH2-deficient macrophages influence tumor features such as clonogenicity and migration." (PMID 39256649, 2024). "This study underlines the potential contribution of IDH2 deficiency in macrophages and its significance in the tumor microenvironment." (PMID 39256649, 2024). "Further, the number of Ki67-expressing cells was significantly reduced in tumor tissues of IDH2-deficient mice." (PMID 39256649, 2024). "Tumor sizes in the IDH2-deficient mouse group were significantly smaller than in the wild-type mouse group." (PMID 39256649, 2024). "The IDH1 and IDH2 genes are characterized by a high rate of gain-of-function mutations across various tumor types." (PMID 39123479, 2024). "Mutations in IDH1 and IDH2 are linked to DNA hypermethylation and impact overall survival (OS) across diverse tumor types." (PMID 39606159, 2024). "In this study, for the first time, we studied the mechanisms through which IDH2 deficiency in macrophages affected tumor growth using IDH2-knockout mice." (PMID 39256649, 2024). "In this study, using a tumor transplantation mouse model, we found that the average tumor size in the IDH2-deficient mouse group was significantly smaller than in the WT." (PMID 39256649, 2024). "These in vitro and in vivo tumor transplantation model findings demonstrated that IDH2 deficiency predominantly increases M1 and inhibits M2 macrophage polarization, suppressing cancer progression." (PMID 39256649, 2024). "In the case of IDH1/IDH2 mutations, further development of the tumor population is directed towards diffuse astrocytoma, anaplastic astrocytoma, or oligodendroglial tumors, while EGFR, CDKN2A/B, and PTEN mutations become early driver events for the GBM." (PMID 35876685, 2023).
tumor (continued). "The median age at baseline was 59 years, 293 (59.8%) were male and 197 (40.2%) female, 51 (11% of 482 patients with available data) had IDH1 or IDH2 mutations detected in their tumours, and 234 (51% of 456) of patients had methylation of the MGMT promotor." (PMID 35804940, 2022). "Analysis of the recurrence revealed an analogous molecular profile: The tumor showed an IDH1 R132H mutation with IDH2 wildtype and TERT C250T promoter mutation." (PMID 35018523, 2022). "Integrated work-up of the first tumor manifestation showed an IDH1 R132H mutation with IDH2 wildtype and TERT C250T promoter mutation." (PMID 35018523, 2022). "In this study, we conducted Sanger sequencing of formalin-fixed paraffin-embedded (FFPE) diagnostic tumor samples using a target-panel to search for recurrent mutations involving the IDH-1/IDH-2, TET-2, DNMT3A and RhoA genes in 59 cases of nMTCL." (PMID 36536430, 2022). "Tumours with IDH1 or IDH2 mutations or those that are IDHwt have significantly different genetic pathways and outcomes in relation to TERT mutation." (PMID 36042521, 2022). "Overall, the prognosis of patients from this tumor class is relatively favorable and comparable to IDH2 mutated tumors." (PMID 36443295, 2022). "In vivo, the tumor-bearing mouse model illustrated the antitumor ability of miR-101 overexpression and IDH2 deficiency." (PMID 36304962, 2022). "Although the GoF variants in IDH1 and IDH2 have been previously identified in the tumors of ~80% of individuals with OD and MS, their role in the tumor formation in these individuals is unclear." (PMID 36480544, 2022). "Here, with the benefit of a large patient cohort, we show that although IDH2 tumours are more commonly associated with TERT mutations, only IDH1 mutations in combination with TERT mutations are associated with significantly reduced survival." (PMID 36042521, 2022). "Using prostate cancer as a model, loss of IDH2 decreased cell growth while increasing tumor cell invasion." (PMID 35356277, 2022). "In conclusion, ten cancer-associated IDH2 point mutants (R140G/Q/W and R172S/K/M/W/G/C/P) have been demonstrated to accumulate 2-HG and promote tumor proliferation by altering a number of downstream cellular activities in the previous studies." (PMID 36335201, 2022). "The underlying mutational pathways of tumours with IDH1 or IDH2 mutations, or those that are IDHwt, differ significantly." (PMID 36042521, 2022). "We utilized in vivo assay to evaluate the tumor growth of NSCLC cells overexpressed with miR-101 or IDH2 deficiency." (PMID 36304962, 2022). "We performed Sanger sequencing analysis of the IDH1/2 gene in the primary tumor and found that the tumor had an IDH2 mutation." (PMID 35505351, 2022). "Despite this, IDH1 and IDH2 tumours have similar molecular ages suggesting that on average, tumours with IDH2 mutations have slower cell division rates." (PMID 36042521, 2022). "Somatic mutations in the isocitrate dehydrogenase genes IDH1 and IDH2 occur at high frequency in several tumour types." (PMID 33740099, 2021). "Mutations in the genes for IDH1 and IDH2 have now been identified in more than 20 different neoplasms." (PMID 35028610, 2021). "The IDH2 mutation exhibited neomorphic activity, as mass spec analysis revealed substantially elevated D-2-HG levels in tumor tissue." (PMID 34616365, 2021). "AG-881 is a small molecular inhibitor of IDH1 and IDH2 mutations, oral administration can reduce the formation of tumor metabolite 2-HG." (PMID 33981605, 2021). "IDH2-R172K mutations in adult hepatocytes can cause the production of 2-HG and create a transformable pre-tumor state through other carcinogenic changes." (PMID 33981605, 2021). "Tumour tissue from forty-five patients were comprehensively analysed for IDH1 or IDH2 mutations and methylation of sixteen sites (CpG’s 74–89) in the CpG island of the MGMT gene." (PMID 34209555, 2021).
tumor (continued). "We re-analyzed the IDH2 status in the tumor from the initial surgery and found an IDH2 R172W mutation, albeit with a very small mutant peak." (PMID 34829476, 2021). "A number of studies have provided strong evidence for the carcinogenic potential of IDH2 mutations, leading to the production of tumor metabolite 2-HG, which changes epigenetic regulation, cancer cell differentiation and cell metabolism." (PMID 33981605, 2021). "Here, we describe the development of a CAR targeting the tumor-specific isocitrate dehydrogenase 2 (IDH2) with R140Q mutation presented on the cell surface in complex with a common human leukocyte antigen allele, HLA-B*07:02." (PMID 34489470, 2021). "Since the mutant peak was small in both cases with detected IDH2 mutation, we suspect that the tumor volume was low in these cases." (PMID 34829476, 2021). "A molecular analysis of the recurrent tumor via Sanger sequencing using a different IDH2 primer revealed an IDH2 R172W mutation, and the pathological diagnosis was anaplastic oligodendroglioma, IDH-mutant and 1p/19q-codeleted." (PMID 34829476, 2021). "Knockdown of IDH2 substantially increases the susceptibility of ferroptosis in cultured tumor cells and in allografted Hepa1–6 tumor in nude mice." (PMID 33801920, 2021). "ctDNA was detected in pre‐operative plasma samples of 31/83 (37%) patients whose tumour harboured an IDH1 or an IDH2 mutation." (PMID 34528398, 2021). "Each tumor included in the study contained a large population of cells with confirmed IDH1 or IDH2 mutations and co-deletion of chromosome 1p and 19q arms, as well as tumor-specific CNVs." (PMID 34948008, 2021). "In a few patients, mutations in other genes, such as WT1 and IDH2, were also found in the corresponding CP samples with lower tumour cell fractions (TCFs) calculated by variant allele frequencies (VAFs) than those found in the BC samples." (PMID 33990592, 2021). "The most frequently mutated metabolic genes in human cancer are those encoding the enzymes isocitrate dehydrogenase 1 (IDH1) and IDH2; these mutations have so far been identified in more than 20 tumor types." (PMID 35028610, 2021). "Mutations of the IDH2 gene are less common, with the most frequent type of tumor being oligodendroglial." (PMID 32856857, 2020). "When the cohort was split into the intrinsic molecular subtypes, high expression of IDH2 protein in luminal B-like was associated with poor outcome in LVI positive tumours (HR 2.1; 95% CI 1.0–4.5; p = 0.044)." (PMID 31599393, 2020). "Mutations in the IDH1 and IDH2 genes have been found in various tumor types and catalyze reduction of a-KG into a structurally similar oncometabolite 2-hydroxyglutarate (2-HG), which probably functions as an α-KG antagonist in numerous metabolic processes." (PMID 31727977, 2019). "More so, when examined carefully, individual IDH2 mutations displayed differential effects on tumor cell growth." (PMID 31105869, 2019). "One tumor (ID75) harbored a somatic IDH2 hot-spot mutation, in line with elevated D-2-hydroxyglutarate." (PMID 31212687, 2019). "Thirty-one cfDNA samples positive for IDH1, KRAS, PIK3CA, NRAS, AKT, BRAF, and IDH2 mutations in tumor tissue were selected for ddPCR, MassARRAY and NGS comparison." (PMID 29535804, 2018). "The largest subgroup comprised 133 tumors (68.9%) and showed the characteristic 1p/19q co-deletion as well as IDH1 or IDH2 mutations in each tumor." (PMID 29631562, 2018). "IDH1/IDH2 mutations are associated with the production of an oncogenic metabolite, D-2-hydroxyglutarate (D-2-HG), which appears to be a critical aspect of tumor development." (PMID 30170631, 2018). "In fact, this precaution is not limited to IDH1 R132 and IDH2 R172 mutations, but should be borne in mind whenever we try to sort driver mutations from passenger ones in any type of tumor." (PMID 28785398, 2017).
tumor (continued). "All the RHOA and IDH2 mutations were confined to the PD1+ cells, indicating that some, including RHOA and IDH2 mutations, being specific events in tumor cells." (PMID 28157189, 2017). "These mutations make IDH1 or IDH2 lose the function of clear metabolites (2HG), resulting the accumulation of 2HG within the tumor." (PMID 28939851, 2017). "IDH2 mutations were also specifically identified in the tumor-cell-enriched cells, suggesting that IDH2 mutations are also tumor-cell-specific events in AITL, although the number of samples was not large enough to allow a definite conclusion." (PMID 28157189, 2017). "Mutations in both IDH1 and IDH2 are ubiquitously expressed within the tumour tissue; moreover, they consistently occur in a heterozygous manner and are most commonly observed in the IDH1 isoform." (PMID 28629182, 2017). "IDH2 has been considered a tumor suppressor because its loss was associated with progression of GC via NF-κB-dependent increases in MMP7 activity." (PMID 27941907, 2016). "This new function generates >100-fold elevated concentrations of D2HG in tumor cells bearing an IDH1 or IDH2 mutation, while there is only trace amount of D2HG in normal cells." (PMID 27316347, 2016). "Somatic mutations in the isocitrate dehydrogenase 1 (IDH1) or IDH2 genes are common in enchondromas and chondrosarcomas, as well as in several neoplasms, including glioma, glioblastoma, acute myeloid leukemia, and intrahepatic cholangiocarcinomas (IHCC)." (PMID 26920730, 2016). "In human HCC, a decreased 5hmC was associated with disease progression through down-regulation of TET1, while high 5hmC and IDH2 levels were associated with a favorable prognosis following tumor resection." (PMID 25918251, 2015). "IDH2 mutations were found in four tumors (4%), with c.515G > A (R172K) in three tumors and c.515G > T (R172M) in one tumor." (PMID 25797251, 2015). "Analysis of the primary tumor sample in isolation suggests a simple organization consisting of a single subclone and a founding clone containing an IDH2 R140L mutation." (PMID 25102416, 2014). "Mutations within this cluster, including IDH2 (R140W), were either present in the primary tumor below the level of detection or are new mutations, possibly induced by cytotoxic chemotherapy." (PMID 25102416, 2014). "In tumours that have these mutations in IDH1 or IDH2, it accumulates to millimolar levels, high enough to detect by a technique called MR spectroscopy, similar to MRI." (PMID 24581008, 2014). "The two most recent studies confirmed that in vivo, IDH2 mutations inhibit differentiation, alter DNA methylation and result in hyper proliferation in diverse tumor contexts." (PMID 25502799, 2014). "As both IDH1 and IDH2 mutations result in the generation of the putative oncometabolite, d-2HG, this oncometabolite can be measured directly in tumor samples and serum." (PMID 23847760, 2013). "To investigate the effects of IDH1 and IDH2 mutations on the CS methylome, we conducted genome-wide DNA methylation (DNAm) profiling of 44 central CS tumour samples using the Illumina Infinium 450 K BeadChips12." (PMID 23863747, 2013). "The elevated 2-HG levels, which are characteristic of IDH1 and IDH2 mutated tumours, is also potentially useful as a biomarker to identify IDH1/IDH2 mutational status or monitor tumour growth or treatment efficacy in a non-invasive way." (PMID 22771539, 2013). "In this tumor type, loss of 5-hydroxymethylcytosine (5-hmC) has diagnostic and prognostic implications, which relates to downregulation of IDH2 and TET family enzymes." (PMID 23533770, 2013). "Mutations of IDH1 and IDH2 in combination with microenvironmental effects in certain tumor types are likely the driver mutations that are responsible for the malignant phenotype, rather than simply epiphenomena." (PMID 23847760, 2013).